KRAS (KRas proto-oncogene, GTPase)
Diseases named in the same sentence as KRAS in open-access papers (continued):
Sharing a sentence is not in itself a finding about the gene and the disease.
lung cancer (continued). "However, the recent clinical approvals of inhibitors targeting KRAS with the specific G12C mutation in lung cancer has shepherded in a new era in precision medicine." (PMID 37141389, 2023). "However, when crossed with mice expressing mutant KRAS in the lung, NSCLC tumors developed, clearly demonstrating that oncogenic mutants of VAV1 act synergistically with mutant KRAS to cause lung cancer." (PMID 37174676, 2023). "In an oncogenic kRas-driven lung cancer mouse model, Atg5 deficiency is associated with an increase in the numbers of early hyperplastic foci and regulatory T cells, and then further antibody treatment or depletion of FoxP3+ cells decrease the hyperplastic lesions to those seen in the controls." (PMID 38067169, 2023). "It is interesting that various mutational profiles of the KRAS mutant lung cancers affect the development of resistance to sotorasib or adagrasib The H95 mutations may confer resistance to adagrasib but does not affect the activity of sotorasib." (PMID 38239281, 2023). "In addition to MIA-PaCa2 cells, they have also tested the AMG 510 resistance in SW1463 human Caucasian rectum adenocarcinoma, LU99 lung giant cell carcinoma, and LU65 lung carcinoma cell lines which have KRAS G12C mutations." (PMID 37396909, 2023). "Pharmacologic inhibition of SHP2, including SHP099 and RMC-4550, could suppress the growth of various tumors harboring KRAS mutations, such as pancreatic and lung cancers, via regulating RAS/MAPK signaling." (PMID 35462913, 2022). "In addition, outcomes of the KEYNOTE189 shows that patients receiving immunotherapy plus chemotherapy have longer mPFS than those receiving chemotherapy (9 vs. 5 months, HR=0.47,95%CI [0.29-0.77]) in KRAS -mutated lung cancer." (PMID 36741723, 2022). "In conclusion, our study shows that MA is a novel EGFR-TKI sensitizer in KRAS-mutated and osimertinib-resistant lung cancer cells by suppressing the KRAS-ERK pathway and inducing ferroptosis via suppressing NRF2-SLC7A11 axis and mitochondrial Ca2+ overload induced-FTH1 pathways." (PMID 36712673, 2022). "We found through the TCGA database that PLA2G4A is highly expressed in KRAS-mutated lung cancer cells, and cPLA2 may be a therapeutic target for KRAS-mutated lung cancer cells." (PMID 36712673, 2022). "The inhibition of CPS1 in lung cancer cells carrying KRAS/LKB1 mutations suppressed tumor growth." (PMID 35251577, 2022). "Mutant allele specific imbalance (MASI) has been observed in combination with KRAS mutation in 58% of lung cancers and has been demonstrated to be mainly caused by uniparental disomy, which results from the complete loss of the wild-type (wt) allele without copy number gain." (PMID 36077640, 2022). "KRAS is frequently mutated and activated in cancers such as pancreatic and lung cancers." (PMID 35177645, 2022). "Therefore, our study explored the role of EGFR inhibitors (afatinib and allitinib) and conducted a comprehensive in vitro and in silico analysis of the molecular mechanisms triggered by KRAS mutations in a panel of lung cancer cell lines." (PMID 35887120, 2022). "The KRAS mutation, a main carcinogenesis driver that has been extensively investigated in the last 30 years, is involved in ~90% of pancreatic cancer, 40% of colon cancer, and 20–30% of lung cancer." (PMID 35563733, 2022). "Therefore, when examining these studies and drawing conclusions, the prognostic role of a KRAS mutation in lung cancer is still debatable." (PMID 35406400, 2022). "Moreover, confocal microscopy analysis in KRAS-mutated primary lung cancer organoids also showed that MA increased lipid peroxidation in organoids." (PMID 36712673, 2022). "Importantly, we found that NF-κB inhibitor, pan-KRAS inhibitor and anti-PD-1 synergized to treat lung cancer deficient of ZNF24." (PMID 36457047, 2022).
lung cancer (continued). "Also, in a group of early stage primary lung cancer patients with potentially resectable tumors (stage I/II/IIIa, n = 173), 7 KRAS (G12/G13) mutations and 1 EGFR L858R mutation were detected." (PMID 36413862, 2022). "Therefore, it will be most relevant to understand the mechanisms underlying potential therapeutic cooperation between KRAS inhibition and immune responses in the setting of lung cancer." (PMID 35857848, 2022). "Indeed, preclinical studies on genetically engineered mouse models assessed that KRAS mutations predisposed to early onset lung cancer." (PMID 35251972, 2022). "Importantly, other frequently mutated forms of KRAS in lung cancer, such as KRAS(G12D) and KRAS(G12V), remain undruggable." (PMID 36377663, 2022). "Similar response patterns have also been described for KRAS‐mutated colorectal and lung cancer." (PMID 35993110, 2022). "The spectrum of KRAS mutations in lung cancer is heterogenous." (PMID 36284306, 2022). "Importantly, the molecular regulation of BCL6 on preRC genes, such as MCM5 was functional and linked to clonogenic growth of KRAS-mutant lung cancer cells." (PMID 36377663, 2022). "Interestingly, there was decreased phosphorylation of FAK and AKT in integrin β1–KO A549 cells prior to treatment with EGF, suggesting that integrin β1 signaling plays a role in the basal activation of these pathways in KRAS-mutated lung cancer cells." (PMID 35763345, 2022). "In recent years, it has become evident that the occurrence of KRAS mutations in lung cancer patients may reflect an opportunity for new drug inhibition, essentially with those directly targeting the G12C variant." (PMID 36077640, 2022). "Mutations in several genes were found to be good prognostic markers for human cancer; examples include mutated KRAS that was correlated with a poor prognosis of pancreatic and lung cancer, and mutated NRAS that was associated with a poor prognosis of metastatic melanoma." (PMID 36430577, 2022). "In addition, Kirsten Rat Sarcoma (KRAS)-mutant lung cancer tumor progression is closely associated with SLC7A11 expression." (PMID 36105219, 2022). "Gefitinib and panobinostat may be effective against gefitinib-resistant lung cancer cells that exhibit mutations in KRAS and EGFR." (PMID 36263432, 2022). "In other words, a lung cancer requires an EGFR mutation plus X addition gene mutations or a KRAS mutation plus Y additional gene mutations where Y > X. WT tumors, lacking any driver genes, require still more mutations (i.e., > Y mutations) to generate a malignant phenotype." (PMID 36612014, 2022). "Since cells harboring KRAS mutation are the main reason for EGFR-TKI resistance with the continuous expression of KRAS, we speculated that the combination treatment of MA and EGFR-TKI osimertinib was a strategy to inhibit KRAS-mutated lung cancer cells." (PMID 36712673, 2022). "However, few effective therapies are available for gain-of-function mutations in KRAS, which occur in approximately 25% of all lung cancer cases." (PMID 36377663, 2022). "The wild-type allele of KRAS is a suppressor in mouse lung cancer." (PMID 36330448, 2022). "Researchers first identified activation of KRAS mutations to cause lung cancers." (PMID 35409064, 2022). "With excellent biocompatibility and high cellular uptake efficiency of NPNCD, the designed NPNCD with KRAS siRNA (NPNCDK) was further conjugated for KRAS-mutated nonsmall cell lung cancer therapy (NSCLC), illustrating excellent gene knockdown efficiency and anticancer effect in vitro." (PMID 35401835, 2022). "KRAS mutations are the most frequent oncogenic driver mutations in human lung cancer cells." (PMID 36074553, 2022). "We were able to detect both G12C & G12V and G12F mutants in publicly available datasets at comparable frequencies to our study 26–28, indicating that the KRAS G12C mutation co-occurrence is a consistent finding across lung cancer studies and patient populations." (PMID 35177674, 2022).
lung cancer (continued). "Similarly, human KRAS-dependent lung cancer cell lines respond to WT1 loss by halting proliferation and undergoing senescence." (PMID 35453662, 2022). "Lung cancer cells with mutated KRAS express high protein levels of YAP/TAZ." (PMID 36263432, 2022). "To investigate the inhibitory effects of MA in lung cancer cells, we treated different types of lung cancer cells, including KRAS-mutated lung cancer cell lines A549 and H157 and EGFR-mutated lung cancer cell lines HCC827 and PC9, with different concentrations of MA for 48 and 72 h." (PMID 36712673, 2022). "STK11 co-mutations have been associated with worse survival in KRAS-mutant lung cancers." (PMID 36284306, 2022). "Suppression of STING in KRAS-driven lung cancer is associated with LKB1 loss, thus, it would be interesting to analyse whether mCRC with KRAS mutations also has a mutation in the LKB1 gene." (PMID 36612217, 2022). "Mutations in lung cancer driver genes (KRAS, EGFR, BRAF, ALK, ROS1, MET, RET, and ERBB2) in the high- and low-risk groups were shown on a waterfall plot, which demonstrated that the low-risk group (20%) harbored a higher EGFR mutation frequency than did the high-risk group (8%)." (PMID 36353226, 2022). "Mutant KRAS (KM) lung cancer (LC) is associated with poor prognosis and resistance to therapy." (PMID 35882862, 2022). "In addition, the combination of MA and osimertinib also inhibited KRAS-mutated lung cancer organoids compared to single-drug treatment groups." (PMID 36712673, 2022). "KRAS mutation positive lung cancer patients remains a huge challenge in clinic." (PMID 36457047, 2022). "With 90% of the patients having adenocarcinoma histology, our data confirmed that KRAS mutations were uncommon in other lung cancer subtypes but could even be found in neuroendocrine and squamous cell tumors in rare cases." (PMID 35887862, 2022). "In 1984, KRAS G12R mutation was identified first in human lung cancer." (PMID 35966590, 2022). "Furthermore, loss of iRhom activity completely suppressed KRAS-driven tumour xenograft growth, demonstrating the requirement of iRhoms in a widely used model of lung cancer." (PMID 35971826, 2022). "Moreover, in a single-center phase II clinical trial on lung cancers harboring the KRAS G12C mutation, a complete response was seen in 3.2% of patients, and a partial response in 33.9% of patients, with a median duration of response of 11.1 months." (PMID 35205778, 2022). "Genomic alterations involving the KRAS gene are common in lung carcinomas, although much is unknown about how different mutations, deletions, and expressions influence the disease course." (PMID 35574381, 2022). "Additionally, by leveraging on the RNAi activity of sncRNAs, synthetic siRNAs and amiRNAs can be utilized to target aberrantly mutated genes, such as KRAS, which are commonly observed in lung cancers." (PMID 33803619, 2021). "Besides EGFR and PIK3CA, other known mutations were detected in KRAS (n = 4; G12V, G12A, G12D, and Q61H), which have all been reported as driver mutations in lung cancer." (PMID 33407425, 2021). "ALKBH5 gain- or loss-of function could effectively reverse LKB1 regulated cell proliferation, colony formation, and migration of KRAS-mutated lung cancer cells." (PMID 34016959, 2021). "Interestingly, a high level of acyl-coA synthetase family member 3 (ACSL3) was observed in human lung cancer, and the enzyme was found to play an essential role in the tumorigenesis of lung cancers bearing KRAS G13D mutation." (PMID 33466836, 2021). "Additionally, this paper will analyze the therapeutic effects of chemotherapy, targeted therapy, and immunotherapy in clinical practice and look to provide individualized treatment strategies for patients with KRAS mutations in lung cancer." (PMID 35070984, 2021). "To investigate whether LKB1 loss affects ALKBH5 and m6A modification, we screened several lung cancer cell lines and categorized them based on KRAS mutation and LKB1 expression status." (PMID 34016959, 2021).
lung cancer (continued). "Lung cancer patients with KRAS mutations are commonly treated with chemotherapy." (PMID 34638488, 2021). "For example, KRAS mutations in lung cancer may be more frequent due to exposure to carcinogens, such as tobacco smoke." (PMID 33801965, 2021). "Although the role of KRAS co-occurring mutations remains to be clarified, it has been described that these alterations may occur clonally or subclonally in lung cancer, a fact that may affect treatment responses." (PMID 34684076, 2021). "However, identification of the major driver mutations in lung cancer patients such as KRAS and EGFR mutations along with expression of PD-L1 would greatly help designing combination treatments for better response." (PMID 33956842, 2021). "In lung cancer, KRAS mutations often play a role in activating the MAP kinase pathway." (PMID 33802234, 2021). "The expression levels of BLT2, 5-LOX, and 12-LOX were increased in two human lung cancer cell lines with activating KRAS mutations (A549 with the KrasG12S mutation, and SK-LU-1 with the KrasG12D mutation) compared with a noncancerous control cell line (BEAS-2B, human bronchial epithelial cell line)." (PMID 34635780, 2021). "Therefore, attention needs to be paid to heterogeneity in the efficacy of immunosuppressive agents in lung cancer patients with KRAS mutations when immunotherapy is administered." (PMID 35070984, 2021). "Furthermore, Blt2 knockout (KO) in a mouse model of KRAS-driven lung cancer was associated with strong suppression of lung tumor formation and IL-6 production." (PMID 34635780, 2021). "The study also revealed prolonged survival of KRAS mutation in lung cancer animal model." (PMID 34395243, 2021). "Moreover, KRAS is the most common form of mutated oncogene in cancer, and the frequency of KRAS mutations is particularly high in colorectal, pancreatic, and lung cancers." (PMID 34775496, 2021). "However, the molecular mechanism underlying the effectiveness of verteporfin in KRAS-mutant lung cancer cells remains obscure." (PMID 33830081, 2021). "While retention of the KRAS WT allele in KRAS mutant tumors has emerged as a factor that modulates resistance to MEK and ERK inhibition in preclinical studies, little is known about the distribution of the WT KRAS allele in lung cancers and its clinical implications." (PMID 34573384, 2021). "More than 30% of non‐small cell lung cancer (NSCLC) patients have KRAS mutations." (PMID 34369083, 2021). "In addition, the list of actionable KRAS mutations in lung cancer will likely increase in the upcoming years." (PMID 35096591, 2021). "The incidence of KRAS gene mutation was 15%-25% in patients with nonsmall cell lung cancer." (PMID 33997043, 2021). "Basic experimental analysis revealed that lung cancer cell lines harboring KRAS G12C or KRAS G12V mutations exhibited increased Ras-related protein (RAL) A/B signaling but decreased PI3K/Akt signaling compared with other KRAS mutant isoforms or WT cell lines." (PMID 35070984, 2021). "Loss of TSC1 synergizes with KRAS mutation to enhance the development of lung cancer in mice." (PMID 34616731, 2021). "This article reviews the latest progress of treatments for NSCLC with KRAS mutation, in order to gain insight into the biological diversity of lung cancer cells and their potential clinical implications, thereby enabling individualized treatment for patients with KRAS-mutant NSCLC." (PMID 35070984, 2021). "Furthermore, the developed CRISPR–Cas12a strategy was successfully applied for the detection of KRAS mutation in tissue samples of lung cancer patients." (PMID 33467412, 2021).
lung cancer (continued). "In line with a previous study describing a protective role for the PERK pathway upon antimetabolites treatment, our results indicate that harsh nutritional microenvironment, reflecting the tumor glucose concentration, indeed protects against PEM in a lung cancer model mutated for KRAS." (PMID 33810430, 2021). "Verteporfin causes unresolved ER stress specific to KRAS-mutant lung cancer cells." (PMID 33830081, 2021). "Moreover, in KRAS-mutated lung cancer cells, miR-34c-3p reduces cell proliferation and increases apoptosis to a greater extent compared to cells expressing wild-type RAS." (PMID 32948832, 2021). "Conversely, the fluorescence intensity of CRISPR–Cas12a with crRNAs specific to wild-type KRAS increased with the reaction time in the wild-type KRAS DNA; however, this did not cause a change in the fluorescence intensity in DNA of the lung cancer cell lines that had the KRAS mutations." (PMID 33467412, 2021). "In addition, ASO-1316 reduced tumorigenicity of KRAS/EGFR mutated lung cancer cell lines in orthotopic mice models." (PMID 33740988, 2021). "The KRAS gene mutation rate in lung cancer patients in exon E2 was higher in whole blood and tissue samples than other exon mutations, while the KRAS gene mutation rate in exons E2 and E3 was significantly higher in patients with lung cancer stages IIB and IA, respectively." (PMID 34217313, 2021). "Because the A549 cell line is a KRAS-mutated lung cancer cell line already, the variants may have generated spontaneously from the in vitro tissue culture." (PMID 34858801, 2021). "Some studies have reported that KRAS mutations may be the targets for preventing and treating KRAS mutant lung cancer and other tumor diseases." (PMID 34616430, 2021). "Moreover, patients with KRAS mutations, the most common driver mutations in lung cancer, demonstrate low response to targeted therapies." (PMID 33956842, 2021). "Moreover, to further demonstrate the linkage between BLT2 expression and KRAS mutation in human lung cancer, we analyzed the patient database stratified by KRAS mutation." (PMID 34635780, 2021). "The driver mutation of lung cancer pathogenesis is often determined to be in KRAS." (PMID 34781949, 2021). "Moreover, KRAS-mutant lung cancer cells exhibited higher Yes-associated protein (YAP) and transcriptional coactivator with PDZ-binding motif (TAZ) levels, and PD-L1 expression was positively correlated with YAP and TAZ in lung cancer cells." (PMID 34073318, 2021). "EGFR and KRAS mutations are the most frequently found mutations in lung cancer." (PMID 34439281, 2021). "Thus, we hope that these treatment strategies will bring clinical benefits to patients with lung cancer having KRAS mutations in Qujing in the future." (PMID 33928034, 2021). "Lung cancer is a highly prevalent cancer type that very often harbours KRAS mutations." (PMID 34781949, 2021). "The results of our study might be biased and may not reflect the genomic characteristics of all lung cancer cases, such as those harboring KRAS mutations, a major genetic alteration in lung adenocarcinoma and smoking-related lung cancer." (PMID 33863951, 2021). "The occurrence of concomitant KRAS mutations in multiple tumours within the same individuals was significantly more frequent than expected by chance, although there were few cases of KRAS mutated lung cancers (P = 0.0049)." (PMID 33707471, 2021). "A preclinical study showed that anlotinib could inhibit proliferation and induce apoptosis of KRAS mutation lung cancer cells through downregulating MEK and ERK." (PMID 34395243, 2021).